CRHR1 (corticotropin releasing hormone receptor 1)
Description:
G protein-coupled receptor for CRH and UCN stress hormones, which plays a central role in whole body adaptation to stress. Ligand binding causes a conformation change that triggers signaling via guanine nucleotide-binding proteins (G proteins) and downstream effectors, such as adenylate cyclase. CRHR1 is mainly coupled to G(s) G protein (GNAS), mediating activation of adenylate cyclase activity and production of cAMP. In some conditions, can also couple to G(q) G protein (GNAQ) and mediate production of diacylglycerol (DAG) and inositol 1,4,5-trisphosphate (IP3) second messengers. CRHR1-dependent signaling is a primary mediator of the neuroendocrine, autonomic (fight-or-flight) and behavioral responses to stress, acting as a key regulator of adaptation by activating the hypothalamus-pituitary-adrenal axis, leading to corticotropin hormone (ACTH) production (By similarity). Mediates both anxiogenic and anxiolytic response to stress in glutamatergic and dopaminergic neurons, respectively (By similarity). CRHR1 also plays a critical role in addiction by mediating the brain's stress response, particularly during withdrawal and relapse: it drives the transition to compulsive drug seeking by increasing anxiety and negative emotional states (By similarity). [Isoform CRF-R3]: Does not bind to CRH with high affinity.
Synonyms: CRH-R-1; CRH-R1; CRF-R-1; CRF-R1; CRFR-1; CRFR1; CRHR; CRF-R; CRF1; CRHR1L
Tractability: Small molecule: a drug acting on it is in phase 2 or 3 trials; a structure with a bound ligand is known; a high-quality ligand is known; it belongs to a druggable protein family. Antibody: its Gene Ontology location is reachable by antibodies, with high confidence; UniProt places it where antibodies can reach, with medium confidence; UniProt predicts a signal peptide or a membrane-spanning region. PROTAC: a small molecule that binds it is known.
Target class: Corticotropin releasing factor receptor; Membrane receptor; Family B G protein-coupled receptor; Peptide receptor (family B GPCR)
Chemical probes: CHEMBL1807053
Gene: Protein-coding gene on chromosome 17 (45,784,277 to 45,835,828, forward strand). Ensembl gene ENSG00000120088.
Subcellular location: Cell membrane
Pathways (Reactome):
Signal Transduction: Class B/2 (Secretin family receptors); G alpha (s) signalling events
Gene Ontology:
Molecular function: corticotrophin-releasing factor receptor activity; G protein-coupled receptor activity; protein binding; corticotropin-releasing hormone binding; corticotropin-releasing hormone receptor activity; G protein-coupled peptide receptor activity; transmembrane signaling receptor activity
Biological process: adenylate cyclase-activating G protein-coupled receptor signaling pathway; cellular response to corticotropin-releasing hormone stimulus; negative regulation of voltage-gated calcium channel activity; activation of adenylate cyclase activity; female pregnancy; general adaptation syndrome; general adaptation syndrome, behavioral process; immune response; parturition; positive regulation of corticotropin secretion; regulation of corticosterone secretion; adrenal gland development; cell surface receptor signaling pathway; cellular response to hormone stimulus; fear response; G protein-coupled receptor signaling pathway; hormone-mediated signaling pathway; positive regulation of synaptic transmission, GABAergic; regulation of transport
Cellular component: membrane; plasma membrane; neuron projection; glutamatergic synapse; postsynaptic density membrane
Genetic constraint (gnomAD): Loss-of-function variants: 27 observed, 56.82 expected, observed/expected ratio (o/e) 0.48, 90% interval 0.35 to 0.65. The upper end of that interval is the gene's LOEUF score, 0.65, which puts it in group 2 of 6, group 1 being the genes least tolerant of losing a copy. Missense variants: 374 observed, 564.83 expected, observed/expected ratio (o/e) 0.66, 90% interval 0.61 to 0.72. Synonymous variants: 194 observed, 226.48 expected, observed/expected ratio (o/e) 0.86, 90% interval 0.76 to 0.96.
Homologues: Orthologues: chimpanzee CRHR1 (99% identical), macaque CRHR1 (99% identical), dog CRHR1 (98% identical), mouse Crhr1 (98% identical), pig CRHR1 (97% identical), rabbit CRHR1 (97% identical), rat Crhr1 (96% identical), guinea pig CRHR1 (91% identical), zebrafish crhr1 (83% identical), tropical clawed frog crhr1.2 (80% identical), Drosophila melanogaster Dh44-R1 (39% identical). Paralogues in human: CRHR2 (67% identical), PTH1R (28% identical), PTH2R (27% identical), SCTR (27% identical), VIPR1 (26% identical), GLP1R (25% identical), GCGR (25% identical), ADGRE3 (25% identical), ADGRE2 (24% identical), ADGRL3 (24% identical), ADGRB2 (24% identical), ADGRE1 (24% identical), and 30 more.
Diseases named in the same sentence as CRHR1 in open-access papers:
CRHR1 is named in the same sentence as 168 diseases in open-access papers, as found by Europe PMC text mining. Sharing a sentence is not in itself a finding about the gene and the disease. The quoted sentences say what the papers report.
Anxiety (174 papers, 2007 to 2026). Intense feelings of nervousness, tension, or panic often arise in response to interpersonal stresses. "Site-specific CRHR1 activation in the amygdala/ITC was associated with increased anxiety-like behavior that was prevented by co-treatment with SCH23390." (PMID 41181610, 2025). "CRHR1 deficiency is linked to reduced anxiety-like behavior, whereas its overexpression correlates with chronic stress." (PMID 40243462, 2025). "Decreased methylation of CRHR1 and associated upregulation of this gene are associated with anxiety-related phenotypes in humans and rodent models." (PMID 39022893, 2024). "The protein coding CRHR1 gene is reported to be associated with anxiety and depression which are common in PD." (PMID 34064523, 2021). "Together, our findings provide evidence that prenatal trauma has a long-term impact on stress axis function and anxiety phenotype associated with altered Crhr1 and Fkbp5 transcripts and promoter methylation." (PMID 33758173, 2021). "In response to stress, hypothalamic and extrahypothalamic CRH is released and binds to CRHR1 in the LC, causing a more tonic phase in these cells and consequential NE release, increased vigilance, hyperarousal and anxiety." (PMID 30804766, 2019). "Our results point to this conclusion for Crhr1 in an allele-specific manner: decrease in anxiety of F1 animals after EE is accompanied by a corresponding decrease in HAB asGEx and increase in LAB asGEx in the BLA." (PMID 24672450, 2014). "Subjects carrying risk alleles for fear and anxiety as described in previous literature, that is both the G-allele of CRHR1 (rs878886) and the short allele of 5HTTLPR, showed the highest context FPS during uninstructed acquisition." (PMID 23717480, 2013). "The cortisol response to acute psychosocial stress, the Trier Social Stress Test, has been reported to be nominally associated with allelic variation in all three CRHR1 SNPs with interactions between trait anxiety and response to stress seen in association with rs110402 variation." (PMID 36285916, 2022). "Crhr1 encodes corticotropin-releasing factor 1 (CRF1); a CRF1 antagonist was anxiolytic in mice, associated with dose-related changes in regional cerebral glucose metabolism in regions involved in mood and anxiety." (PMID 34276303, 2021). "We found a significant association (p < 0.001) between CRHR1 gene variants rs878886 and rs16940665, or haplotype rs878886*C–rs16940665*T, and tianeptine antidepressant response and remission according to the hospital anxiety and depression scale." (PMID 33154348, 2020). "Hence, our findings indicate that these two polymorphisms (CRHR1 - rs878886 and 5HTTLPR) that both have been previously associated with fear and anxiety, are interactively involved in an exaggerated fear response to a threat context." (PMID 23717480, 2013). "Hence, future studies on the role of CRHR1 in fear and anxiety would greatly benefit from molecular research investigating regulatory effects of rs878886 and other polymorphisms within the CRHR1 sequence." (PMID 23717480, 2013). "Moreover, in this particular study the selection of the candidate genes was based on prior genetic association with anxiety (5HTTLPR: /CRHR1:)." (PMID 23717480, 2013). "Moreover, the inability to appropriately condition to a danger cue that depended on CRHR1 (rs878886) was associated with heightened contextual anxiety in interaction with genetic variability in the serotonin transporter." (PMID 23717480, 2013). "We then assessed CeA expression of stress-related genes, including CRF (Crh), CRF1 receptor (Crhr1), Fkbp5, brain-derived neurotrophic factor (Bdnf), and nuclear receptor subfamily 3 group C member 1 (Nr3c1; which encodes the GR), which are known to modulate anxiety and alcohol drinking." (PMID 38509197, 2024).
Anxiety (continued). "Moreover, gestational hypoxia-induced sex-differential methylation of CRHR1 in the paraventricular nucleus (PVN) linked to anxiety-like behavior in adult offspring, and overactivation of CRHR1 and aquaporin was in cerebral cortex by hypoxia-induced brain edema." (PMID 36147561, 2022). "CRHR2 down-regulation may also lead to hypercortisolemia via an inappropriately high-normal CRH and ACTH, via CRHR1 pituitary activation, and simultaneously drive central and peripheral catecholamine secretion, which can further mediate the anxiety-causing and hyperglycemic effects." (PMID 36077219, 2022). "Corticotropin-releasing hormone (CRH) and its receptor, CRHR1, are known to be involved in the regulation of anxiety." (PMID 40243462, 2025). "The CRH/CRHR1 system is involved in stress responses, and an imbalance in CRHR1 expression can lead to heightened anxiety and stress reactivity." (PMID 40243462, 2025). "In conclusion, our results support the well-established role of amygdala CRHR1 systems in mediating anxiety- and stress-related responses and their overactivation in alcohol dependence." (PMID 41181610, 2025). "Another study demonstrated an anxiogenic effect of CRH/CRHR1 when the knockdown of CRHR1 in the basolateral Amy led to decreased anxiety-like behavior, and activation of the CRHR1 signaling pathway in the basolateral Amy and BNST induced anxiety-like behavior." (PMID 39595978, 2024). "Corticotropin releasing hormone receptor 1 (CRHR1) antagonists such as antalarmin and miR-34b, which targets CRHR1 and negatively regulates its mRNA, have been reported to alleviate anxiety." (PMID 39153974, 2024). "It has been reported that miR-483-5p and miR-699p-5p influence anxiety induced by physical or psychological stress via targeting corticotropin-releasing hormone receptor 1 (Crhr1) and Adrenoceptor Alpha 1B (Adra1b) mRNAs." (PMID 36979479, 2023). "CRH, released by the bed nucleus of the stria terminalis (BnST), modulates stress-related anxiety via CRHR1 located in the nucleus accumbens and CRHR2." (PMID 37508942, 2023). "CRHR2 plays a role in counteracting the effect of CRHR1 activation, which induces anxiety-like behavior and stress response." (PMID 37358267, 2023). "Male rats, exposed to prenatal hypoxia stress, had a higher CRHR1 mRNA expression in the paraventricular nucleus of the hypothalamus than male control rats and showed higher anxiety." (PMID 36275850, 2022). "The most commonhypothesis – CRHR2 activation is responsible for providingphysiological and psychological homeostasis and counteractsthe initial effects of CRHR1 activation, which induce stressresponse and anxiety-like behavior (Bale, Vale, 2004)." (PMID 34901719, 2021). "While CRH-mediated activation of CRHR1 increasesbasal and stress-induced anxiety in many brain areas, includingBLA, BNST, and PAG, a more complex picture is observedfor other brain regions." (PMID 34901719, 2021). "In rodents, early life stress has been found to induce an increased anxiety-like behavior and cognitive deficits in association with increased central CRH and CRHR1 expression." (PMID 33758173, 2021). "Based on the plethora of preclinical evidence implicating the CRH signaling pathway in maladaptive behaviors, several clinical studies have investigated CRHR1 antagonists as potential therapeutic targets for the treatment of anxiety, PTSD, and AUDs." (PMID 33867924, 2021). "EA significantly reduced the expression of CRH and CRHR1 mRNA in the paraventricular nucleus of the hypothalamus in a rat model of stress-induced anxiety." (PMID 34306138, 2021). "Pearson’s correlation index between anxiety-like behavior z-score, Nr3c1, Crh, Crhr1, and Corticosterone." (PMID 33304248, 2020). "Lastly, our study identified sites through which CRHR1 controls anxiety and provides a neuronal mechanism for the anxiolytic properties of CRHR1-directed therapeutics." (PMID 29904149, 2020).
Anxiety (continued). "The Crhr1 promoter region lies within a CpG island, and behavioral experiences that alter anxiety-like behavior have been shown to increase methylation on one CpG site located 1,348 bases upstream of the Crhr1 translation start in the amygdala." (PMID 29497387, 2018). "Functional in vivo experiments have previously revealed bidirectional models for the role of CRHR1 on the cellular level in anxiety studies." (PMID 29180955, 2017). "The corticotropin-releasing hormone receptor 1 (CRHR1) is associated with mammalian stress, and knockout mice have lower anxiety; the fly homolog is the diuretic hormone 44 receptor 1 (DH44-R1)." (PMID 27020741, 2016). "Along these lines, Magalhaes and colleagues illustrated that CRHR1 regulates anxiety-related behavior sensitizing 5HT2R signalling, which required intact PDZ binding motifs of both receptors." (PMID 26352593, 2015). "We have recently identified a bidirectional control of anxiety-related behavior by CRHR1 in anxiogenic glutamatergic and anxiolytic dopaminergic circuits, suggesting distinct CRHR1-dependent signaling pathways." (PMID 26352593, 2015). "Recently, it has been shown that the expression of Crhr1 in the amygdala is crucial for the anxiety state." (PMID 24672450, 2014). "Depending on its location, CRHR1 may play a dual role (anxiolytic or anxiogenic) in the development of anxiety through glutamatergic or dopaminergic antagonistic activation, balancing the emotional response to stress." (PMID 41614899, 2026). "Thus, CRHR1 impacts NREMS by modulating thalamic excitability, providing a potential target to stabilize sleep impairments associated with stress and anxiety." (PMID 40830097, 2025). "In the basolateral amygdala (BLA), CRHR1 plays a pivotal role in mediating anxiety-like behaviors." (PMID 40243462, 2025). "As HPA axis activation has been implicated in both CKD and anxiety, the expression of arginine vasopressin (Avp), corticotropin-releasing hormone (Crh), and CRH receptor 1 (Crhr1) and 2 (Crhr2) genes was determined in the amygdala, followed by analysis of protein expression." (PMID 37989901, 2024). "Increased hypothalamic CRHR1 mRNA expression was also found exclusively in male rats after prenatal stress, which was attributed to differential epigenetic modifications and accompanied by higher anxiety." (PMID 36275850, 2022). "Moreover, we have shown previously that demethylation of the Crhr1 promoter in the PVN is also involved in male offspring anxiety behavior as a result of gestational hypoxia." (PMID 36147561, 2022). "This demonstrates the importance of BST CRH neuron activation in areas beyond the regulation of anxiety-like behavior, and CRHR1 antagonists remain a potential avenue for the development of therapeutics that help prevent the reinstatement of drug-seeking behavior." (PMID 33867924, 2021). "Additionally, limbic CRH and CRH receptor 1 (CRHR1) have also long been identified as central regulators of anxiety." (PMID 29904149, 2020). "Whether CRHR1 signaling in dopaminergic neurons retains anxiety-suppressing properties following exposure to chronic stress remains to be investigated." (PMID 31619956, 2019). "Chronic variable stress in the third week of pregnancy in rats leads to increased anxiety-like behavior in the elevated-plus-maze (EPM) in young adult offspring and is associated with increased CRH and CRHR1 in the amygdala of female offspring and CRHR2 expression in offspring of both sexes." (PMID 26082698, 2015). "Finally, while no significant changes in anxiety-like behaviours were observed in this study, several genes associated with anxiety, such as CRHR1, NR3C1, NR3C2, were altered in a region and time dependent manner injured mice." (PMID 40375338, 2025). "Thus, CRHR1 may play a bidirectional role in anxiety, as an imbalance between CRHR1-controlled anxiogenic glutamatergic and anxiolytic dopaminergic systems may lead to emotional impairments." (PMID 38927393, 2024).